VASH1 (vasohibin 1)
Diseases named in the same sentence as VASH1 in open-access papers (continued):
Sharing a sentence is not in itself a finding about the gene and the disease.
Insulin resistance (6 papers, 2017 to 2025). Increased resistance towards insulin, that is, diminished effectiveness of insulin in reducing blood glucose levels. "Other findings showed evidence that miR-335-5p inhibited vasohibin-1, ultimately stimulated the transforming growth factor‐β signaling, resulting in the suppressed β-cell GSIS and aggravated insulin resistance in GDM mice." (PMID 38260139, 2023). "VASH1, a negative feedback regulator of angiogenesis, was reported to play roles in regulating glucose tolerance and insulin resistance in recent studies." (PMID 41299998, 2025).
breast carcinoma (5 papers, 2015 to 2024). "For example, miR-4530 could directly target the 3′-UTR of VASH1 and promote angiogenesis, inhibit proliferation, and induce apoptosis by suppressing the expression of VASH1 in breast carcinoma cells." (PMID 29467441, 2018). "To further confirm VASH1 expression in cancer cells, we first determined the gene expression levels of VASH1-A and VASH1-B in different cancer cell lines, including colon, prostate, and breast cancers, using Real-time PCR analyses." (PMID 25797264, 2015).
diabetes (5 papers, 2014 to 2021). "Inhibition studies with soluble Tie2-Fc or VEGF-trap further supported the role of VASH1-mediated up-regulation of angiogenic factors on diabetic ED." (PMID 33441910, 2021). "Diabetes-induced upregulation of VEGF-A in kidneys was enhanced in VASH1 heterozygous knockout mice." (PMID 29937525, 2018). "Diabetes-induced mesangial type IV collagen accumulation and glomerular monocytes infiltration were also suppressed by treatment with Ad-VASH1." (PMID 28835895, 2017). "In type 2 diabetic (db/db) mice, adenoviral overexpression of VASH1 relieved a diabetes-induced podocyte injury." (PMID 28835895, 2017). "Streptozotocin-induced type 1 diabetic VASH1 heterozygous knockout mice (VASH1+/−) or wild-type diabetic mice were sacrificed 16 weeks after inducing diabetes." (PMID 25255225, 2014). "Indeed, diabetes-induced albuminuria and glomerular alterations were ameliorated in VASH2 homozygous knockout mice, which is completely the opposite from VASH1 heterozygous knockout mice." (PMID 29937525, 2018).
renal cell carcinoma (5 papers, 2015 to 2024). "In the pathological specimens of renal cell carcinoma, there was a significant negative correlation between VASH-1 and HIF1α." (PMID 32754616, 2020).
fibrosis (3 papers, 2014 to 2024). the formation of excess fibrous connective tissue in an organ or tissue in a reparative or reactive process. "Interstitial fibrosis, the accumulation of type I and type III collagen and monocytes/macrophages infiltration in the obstructed kidneys (OBK) were significantly exacerbated in VASH‐1+/− mice compared with WT mice (Day 7)." (PMID 24973329, 2014).
Lewis lung carcinoma (3 papers, 2009 to 2021). "Knockdown of VASH1 decreased the expression of zonula occludens-1, a tight junction protein, in endothelial cells and increased transmigration of Lewis lung carcinoma cells across the endothelial cell monolayer." (PMID 33441910, 2021). "Alternatively, with regard to its function, we showed that increased tumor growth and tumor angiogenesis were evident when Lewis lung carcinoma (LCC) cells were inoculated into VASH1 (−/−) mice." (PMID 24066086, 2013). "When Lewis lung carcinoma (LLC) cells were inoculated in the footpad to observe spontaneous metastasis, a significant increase in lung metastasis together with inguinal lymph node metastasis was evident in the VASH1 (−/−) mice." (PMID 24066086, 2013).
neuroendocrine tumors (3 papers, 2022 to 2026). "This seems to be important in the case of the VASH-1 and serotonin correlation, as usually low values of neuroendocrine tumor markers in clinical practice are associated with a better prognosis in these patients." (PMID 35372578, 2022). "In pathological contexts, VASH-1 exhibits paradoxical expression patterns-downregulated in neuroendocrine tumors but upregulated in bladder cancer-and demonstrates tissue-specific functions that either inhibit or promote angiogenesis." (PMID 41737219, 2026). "It was confirmed that the VASH-1/CD31 ratio can be a reliable indicator for the assessment of neovascularization in neuroendocrine tumors." (PMID 37568488, 2023). "This is the first study of the VASH-1 concentration analysis in the blood serum in a group of patients with neuroendocrine neoplasms." (PMID 35372578, 2022). "The study also found a weak negative correlation between the concentration of serotonin, one of the selected markers of neuroendocrine neoplasms, and the concentration of VASH-1." (PMID 35372578, 2022). "VASH-1/CD31 has been shown to be an excellent immunohistochemical marker for the characterization of neovascularization in neuroendocrine neoplasms." (PMID 35372578, 2022). "The highest concentration of VASH-1 was found in patients with pancreatic NETs as compared to neuroendocrine neoplasms with a different primary localization site (p < 0.05)." (PMID 35372578, 2022). "Patients with neuroendocrine tumors showed lower serum level of VASH-1 in comparison to healthy volunteers." (PMID 35372578, 2022). "To evaluate a broader role of VASH-1 and VEGF-A in the pathogenesis of neuroendocrine tumors, we plan to expand our study, e.g., include also other factors." (PMID 35372578, 2022).
renal fibrosis (3 papers, 2014 to 2024). A final common manifestation of a wide variety of chronic kidney diseases characterized by glomerulosclerosis and tubulointerstitial fibrosis. "Thus, in the present study, we investigated the functional role of endogenous VASH‐1 in regulating the inflammation and renal fibrosis in a mouse model of UUO using VASH‐1 deficient mice." (PMID 24973329, 2014). "Both miR-10a/b can negatively regulate the target gene VASH-1, thereby promoting the phosphorylation of Smad3 and driving the development of renal fibrosis." (PMID 38791272, 2024). "Furthermore, the renal and glomerular hypertrophy, glomerular accumulation of mesangial matrix and type IV collagen and activation of renal TGF-β1/Smad3 signaling, a key mediator of renal fibrosis, were exacerbated in the diabetic VASH1+/− mice compared with the diabetic wild-type littermates." (PMID 25255225, 2014). "Although we evaluated the regulatory role of endogenous VASH‐1 on the tubulointerstitial alterations induced by UUO, an evaluation in other models of renal fibrosis may be warranted." (PMID 24973329, 2014).
atherosclerosis (2 papers, 2016 to 2023). A disease characterized by the build-up of fatty material and calcium deposition in the arterial wall resulting in partial or complete occlusion of the arterial lumen. "Here, we added VASH1 to the list of miR‐22 targets that are downregulated during endothelial cell senescence and that might be response for aging‐associated vascular diseases including atherosclerosis." (PMID 27325558, 2016). "VASH1 is involved in tumorigenesis, atherosclerosis, age-dependent macular degeneration, and diabetic retinopathy." (PMID 37063972, 2023). "We then advanced our analysis to examine the development of atherosclerosis by crossing Vash1(−/−) and ApoE(−/−) mice." (PMID 27325558, 2016).
chronic kidney disease (2 papers, 2014 to 2025). Impairment of the renal function secondary to chronic kidney damage persisting for three or more months. "Chronic kidney disease (CKD) is characterized by a progressive loss of renal function, and dysregulation of angiogenesis is usually found to aggravate CKD development; therefore, VASH-1 also plays a critical role in this process because it is a negative regulator of angiogenesis." (PMID 40497943, 2025). "In the present study, we aimed to define the clinical significance of VASH-1 and SVBP in patients with chronic kidney disease (CKD)." (PMID 24915146, 2014).
endometriosis (2 papers, 2023 to 2025). The growth of functional endometrial tissue in anatomic sites outside the uterine body. "MiR-143-3p was confirmed to directly bind to vasohibin 1 (VASH1) via activation of TGF-β signaling, promoting EMT, cell migration, and invasion in endometriosis." (PMID 37834449, 2023). "However, functional studies suggest that miR-143-3p directly targets Vasohibin 1 (VASH1), activating TGF-β1 signaling and promoting cell migration and invasion in endometriosis." (PMID 40305232, 2025).
esophageal cancer (2 papers, 2022). A primary or metastatic malignant neoplasm involving the esophagus. "Also, VASH1 in esophageal cancer, the exact mechanism of which needs to be followed up with continued research." (PMID 36504559, 2022). "have come to similar conclusions in esophageal cancer, suggesting that VASH1 has a special biological role and may be a potential target for tumor therapy." (PMID 36504559, 2022).
Hypertension (2 papers, 2012 to 2024). The presence of chronic increased pressure in the systemic arterial system. "We noted earlier that VASH1 neither instigates such vascular regression nor causes proteinuria and hypertension." (PMID 23056314, 2012).
lymph node metastasis (2 papers, 2022). "The results demonstrated that VASH-1 positivity in the NEC components was greater than that in the non-NEC components of the same MiNEN cases, but was not necessarily associated with lymphovascular invasion and/or lymph node metastasis." (PMID 35565281, 2022).
pulmonary fibrosis (2 papers, 2014 to 2015). Chronic progressive interstitial lung disorder characterized by the replacement of the lung tissue by connective tissue, leading to progressive dyspnea, respiratory failure, or right heart failure. "And further, transfection of the vasohibin-1 gene could attenuate bleomycin-induced pulmonary fibrosis via inhibition of angiogenesis." (PMID 26360832, 2015).
rectal cancer (2 papers, 2015 to 2025). A primary or metastatic malignant neoplasm that affects the rectum. "Many proteins are reported to be associated with the prognosis of patients with rectal cancer including vasohibin-1 and miR-25." (PMID 25790262, 2015).
type 2 diabetes (2 papers, 2014 to 2020). "In our previous studies employing adenoviral vectors encoding human VASH1 (hVASH1) in the murine type 1 and type 2 diabetes models, we observed therapeutic effects on diabetic renal alterations." (PMID 25255225, 2014). "Contrastingly, immunohistochemical displayed TGFβ1 has also been significantly suppressed, proving that VASH-1 has the inhibitory effect of renal interstitial fibrosis in type 2 diabetes." (PMID 32754616, 2020). "Obese type 2 diabetic mice, after treatment of injecting with coding Vash1 gene viral vectors, appeared glomerular hypertrophy, glomerular ultrafiltration, proteinuria, and accumulation of mesangial matrix and significantly suppressed collagen type IV." (PMID 32754616, 2020). "First, we evaluated the regulatory role of endogenous VASH1 in a type 1 diabetic nephropathy model, and the use of distinct diabetic animal models, i.e. type 2 diabetes, should be considered in the future to verify our findings." (PMID 25255225, 2014).
Ureteral obstruction (2 papers, 2014 to 2017). Obstruction of the flow of urine through the ureter. "In the present study, we evaluated the role of endogenous VASH‐1 in regulating the tubulointerstitial alterations induced by unilateral ureteral obstruction (UUO), and assessed its role on fibrogenesis and the activation of Smad3 signaling in renal fibroblasts." (PMID 24973329, 2014). "Thus, endogenous VASH1 probably prevents both angiogenic and inflammatory responses in diabetic glomeruli, as similar anti-inflammatory effect of endogenous VASH1 was also confirmed in a unilateral ureteral obstruction model." (PMID 28835895, 2017).
acute kidney injury (1 paper, 2025). Sudden and sustained deterioration of the kidney function characterized by decreased glomerular filtration rate, increased serum creatinine or oliguria. "For example, VASH-1 deficiency exacerbates cisplatin-induced acute kidney injury (AKI) due to the improper maintenance of peritubular capillary integrity following cisplatin-induced EC stress." (PMID 40497943, 2025).
Alzheimer disease (1 paper, 2022). A progressive, neurodegenerative disease characterized by loss of function and death of nerve cells in several areas of the brain leading to loss of cognitive function such as memory and language. "In addition, the VASH1/2-SVBP carboxypeptidases have been recently identified as a tubulin detyrosinating complexes suggesting that also drugs able to modulate tubulin carboxypeptidase activity may offer a valuable new approach for therapeutic intervention in Alzheimer’s disease." (PMID 35148384, 2022).
arterial disease (1 paper, 2016). "We therefore examined the role of VASH1 in the age‐related arterial disease, namely arteriosclerosis." (PMID 27325558, 2016).
breast ductal carcinomas in situ (1 paper, 2012). "The number of microvessels that are positive for vasohibin-1 (a negative feedback regulator of angiogenesis) and vasohibin-1 mRNA levels in 17 breast ductal carcinomas in situ (DCIS) is significantly lower compared to those of 22 invasive ductal carcinomas." (PMID 22007214, 2012).
colorectal cancer (1 paper, 2022). A primary or metastatic malignant neoplasm that affects the colon or rectum. "VASH-1 expression was reported to be positively correlated with VEGF-A in colorectal cancer tissues and was significantly higher compared to adjacent tissues." (PMID 35372578, 2022). "Similarly, another study showed that high VASH-1 expression in colorectal cancer increased the malignancy potential and promoted the formation of metastasis." (PMID 35372578, 2022).
corneal diseases (1 paper, 2010). "Additional studies are needed to elucidate the mechanism by which vasohibin-1 works and find ways to utilize its anti-angiogenic activity for the treatment of corneal diseases." (PMID 20680097, 2010). "Therefore, vasohibin-1 therapy may be useful as an angiogenic regulator for treating corneal diseases that exhibit neovascularization." (PMID 20680097, 2010).
endothelial dysfunction (1 paper, 2016). In vascular diseases, endothelial dysfunction is a systemic pathological state of the endothelium (the inner lining of blood vessels) and can be broadly defined as an imbalance between vasodilating and vasoconstricting substances produced by (or acting on) the endothelium. "Thus, we propose this decrease in VASH1 expression to be one of the causes of age‐related endothelial dysfunction and may relate to age‐associated vascular diseases." (PMID 27325558, 2016).
epithelial ovarian tumors (1 paper, 2023). "Here, we identified the tumor suppressor part of VASH1 across cancers, including epithelial ovarian tumors." (PMID 38010374, 2023).
erectile dysfunction (1 paper, 2025). Persistent or recurrent inability to achieve or to maintain an erection during sexual activity. "This distinctive feature of VASH-1 lays the groundwork for future studies of erectile dysfunction mechanisms and treatments." (PMID 40497943, 2025). "VASH-1 injection enhanced intracavernous angiogenesis, ultimately reversing erectile dysfunction." (PMID 40497943, 2025).
glioma (1 paper, 2022). A benign or malignant brain and spinal cord tumor that arises from glial cells (astrocytes, oligodendrocytes, ependymal cells). "Univariate results showed that high expression of VASH1 in gliomas was significantly associated with poor LGG prognosis." (PMID 36504559, 2022). "In vitro experiments showed that knockdown of VASH1 expression in glioma cell lines caused increased glioma cell proliferation, invasion, and migration capacity." (PMID 36504559, 2022). "Multivariate and the Nomogram model showed that high VASH1 expression was an independent risk factor for glioma prognosis and had better prognostic prediction efficacy in different LGG Patient cohorts (HR = 4.753 and P=0.002)." (PMID 36504559, 2022). "First, we used real-time PCR and Western-blot to detect the expression of VASH1 mRNA and protein in common human glioma cell lines (A-172, U-251, and U-87) and found that the mRNA and protein expression of VASH1 were highest in the U-251 cell line." (PMID 36504559, 2022). "Our study aimed to investigate the expression and prognostic value of the VASH1 in Lower-Grade Glioma (LGG), to explore its functional network in LGG and its effects on biological behaviors." (PMID 36504559, 2022). "To further understand the effect of VASH1 expression on the biological behavior of glioma cells, we have constructed VASH1 knockdown glioma cell lines for functional experiments." (PMID 36504559, 2022). "Meanwhile, we used the CCLE database, the results showed that VASH1 expression was elevated in different glioma cell lines." (PMID 36504559, 2022). "We speculate that the mechanism of action of VASH1 in glioma may have some correlation with IDH1 and may provide a potential molecular marker for risk stratification of high-risk gliomas." (PMID 36504559, 2022). "Meanwhile, the biological effects of VASH1 on glioma cells were confirmed by in vitro experiments." (PMID 36504559, 2022). "Therefore, we further investigated the effects of VASH1 on the migration and invasion capacity of glioma cells in vitro." (PMID 36504559, 2022). "According to the observations of two pathologists (unknown patient information), immunohistochemical results showed that VASH1 protein was mainly brown positive in the nucleus and cytoplasm of glioma cells and endothelial cells." (PMID 36504559, 2022). "Interestingly, VASH1-SVBP plays a regulatory role in α-tubulin tyrosineization and induces the ossification of microtubulins by the polymerization of tubulins, a morphological alteration associated with reduced invasion of gliomas." (PMID 36504559, 2022). "Additional studies are required to assess the function of VASH1 in LGG progress and in regulating the glioma tumor microenvironment." (PMID 36504559, 2022). "However, the mechanism of action of VASH1 in gliomas has not been elucidated." (PMID 36504559, 2022).
head and neck squamous cell carcinoma (1 paper, 2025). A squamous cell carcinoma that arises from any of the following anatomic sites: lip and oral cavity, nasal cavity, paranasal sinuses, pharynx, larynx, and salivary glands. "VASH1 and VASH2 play contrasting roles in angiogenesis, a critical process driving tumor growth and metastasis in head and neck squamous cell carcinoma (HNSCC)." (PMID 40483461, 2025).
hemangioma (1 paper, 2020). A benign vascular lesion characterized by the formation of capillary-sized or cavernous vascular channels. "Thus, further research is needed to clarify the apparent discordant role on inhibition and proliferation of VASH1 on endothelial cells from hemangiomas." (PMID 32094357, 2020).
IgA nephropathy (1 paper, 2026). "This study delivers a reproducible 9-gene machine-learning classifier for precise IgA nephropathy diagnosis and highlights HLA-DRA and VASH1 as promising biomarkers." (PMID 41803714, 2026).
injury (1 paper, 2012). Damage inflicted on the body as the direct or indirect result of an external force, with or without disruption of structural continuity. "We therefore judge that the protective action of VASH1 in the paraquat-induced acute lung injury occurred mainly through ECs." (PMID 23056314, 2012).
kidney cancer (1 paper, 2022). Primary or metastatic malignant neoplasm involving the kidney. "In the kidney cancer model, VASH1 overexpression is able to inhibit tumor growth and promote apoptosis by blocking the cell cycle at the G0/G1 stage." (PMID 36504559, 2022).